PGR (progesterone receptor)
Diseases named in the same sentence as PGR in open-access papers (continued):
Sharing a sentence is not in itself a finding about the gene and the disease.
triple-negative breast carcinoma (continued). "Triple-negative breast cancer (TNBC) is defined by lack of ER (estrogen receptor) and PR (progesterone receptor) expression and HER2 (human epidermal growth factor receptor 2) overexpression (or HER2 gene amplification)." (PMID 37537339, 2023). "Triple-negative breast cancer (TNBC) represents 15–20% of all breast cancers (BCs); it is characterized by the lack of expression of estrogen receptor (ER), progesterone receptor (PR), and the absence of HER2 gene amplification." (PMID 37684252, 2023). "Triple-negative breast cancer (TNBC) assigns to a subgroup of breast cancer (BC) determined by the absence of estrogen receptor (ER), progesterone receptor (PR), and human epidermal growth factor receptor 2 (HER2)." (PMID 36939902, 2023). "Triple-negative breast cancer (TNBC) is characterized by lack of expression of the estrogen receptor (ER), the progesterone receptor (PR) and HER-2." (PMID 37391408, 2023). "Triple-negative breast cancer (TNBC) is defined by immunohistochemistry (IHC) as the lack of expression of estrogen receptor (ER), progesterone receptor (PR), and HER2." (PMID 37264313, 2023). "Triple-negative breast cancer (TNBC) is a subtype of BC that does not express estrogen receptor (ER), progesterone receptor (PR), or human epidermal growth factor receptor 2 (HER-2), and, therefore, is not sensitive to endocrine therapy or HER2 treatment." (PMID 36986408, 2023). "One common subtype of breast cancer is triple-negative breast cancer (TNBC), which has no progesterone receptor (PR), estrogen receptor (ER), or human epidermal growth factor 2 (HER2)." (PMID 37764312, 2023). "Triple-negative breast cancer (TNBC), representing approximately 15–20% of all breast cancer (BC) diagnosed worldwide, is defined by the lack of estrogen receptor (ER), progesterone receptor (PR) and epidermal growth factor receptor 2 (HER2)." (PMID 37443843, 2023). "In general, tumours that neither express oestrogen receptor (ER), progesterone receptor (PR), nor human epidermal growth factor receptor 2 (HER2) are defined as triple-negative breast cancer (TNBC)." (PMID 35204811, 2022). "Triple-negative breast cancer (TNBC) is characterized by the lack of expression of estrogen receptor (ER), progesterone receptor (PR), and epidermal growth factor receptor 2 (HER2)." (PMID 35440077, 2022). "Triple negative breast cancer (TNBC) does not express estrogen receptor (ER) and progesterone receptor (PR) and is characterized by the absence of HER2 overexpression/ amplification." (PMID 35989353, 2022). "Previous work focused on the role of differential miRNA expression in the triple-negative breast cancer (TNBC) histologic subtype (estrogen receptor–negative, progesterone receptor–negative, HER2-negative." (PMID 35992327, 2022). "Malignant breast cancers are difficult to cure, especially highly metastatic triple-negative breast cancers (TNBC) lacking estrogen receptor (ER), progesterone receptor (PR) and human epidermal growth factor receptor 2 (HER2) molecules as therapeutic targets." (PMID 35915084, 2022). "Triple-negative breast cancer (TNBC) is ineligible for hormonal therapy and Her-2-targeted therapy due to the negative expression of the estrogen receptor, progesterone receptor, and human epidermal growth factor receptor-2." (PMID 36776368, 2022). "Triple negative breast cancer (TNBC), is a particularly aggressive subtype of breast cancer which is Oestrogen Receptor negative (ER), Progesterone Receptor negative (PR) and does not overexpress the Human Epidermal Growth Factor Receptor 2 (HER2)." (PMID 34678587, 2022). "Breast cancer with negative estrogen receptor (ER), negative progesterone receptor (PR), and negative human epidermal growth factor receptor 2 (HER2) expression is pathologically defined as triple-negative breast cancer (TNBC)." (PMID 35115500, 2022).
triple-negative breast carcinoma (continued). "Triple negative breast cancer (TNBC) is characterized by the lack of estrogen and progesterone receptor expression and lacks HER2 overexpression or gene amplification." (PMID 35987766, 2022). "Triple negative breast cancer (TNBC) is a special molecular subtype pattern which is characteristic of negative for estrogen receptor (ER), progesterone receptor (PR) and human epidermal growth factor receptor 2 (HER-2)." (PMID 36424626, 2022). "Triple-negative breast cancer (TNBC) represents a lack of estrogen receptor (ER), progesterone receptor (PR), and human epidermal growth factor receptor 2 (HER2)." (PMID 36612209, 2022). "Triple-Negative Breast Carcinoma (TNBC) is characterized by an absence of estrogen receptor, progesterone receptor and HER2 neu expression, with distinct molecular, histological and clinical features, aggressive clinical course and a poor prognosis." (PMID 35463732, 2022). "Triple-negative breast cancer (TNBC) is a subtype of breast cancer with negative estrogen receptor (ER), progesterone receptor (PR), and human epidermal growth factor receptor 2 (HER-2) expression." (PMID 35965522, 2022). "Triple-negative breast cancer (TNBC) is defined by the absence of estrogen receptor (ER), progesterone receptor (PR) and human epidermal growth factor receptor-2 (HER2), and accounts for 20% of all invasive breast cancers." (PMID 35774393, 2022). "Triple-negative breast cancer (TNBC) is defined by the lack of estrogen receptor (ER) and progesterone receptor (PR) expression and HER2 gene amplification." (PMID 36531080, 2022). "Triple-negative breast cancer (TNBC) refers to the lack of the expression of estrogen receptor (ER), progesterone receptor (PR), and human epidermal growth factor receptor 2 (HER2) in breast tumors." (PMID 35814418, 2022). "Triple negative breast cancer (TNBC) refers to breast neoplasms that do not express estrogen receptor (ER), progesterone receptor (PR), or human epidermal growth factor receptor 2 (HER2) on their cell surface." (PMID 35267561, 2022). "Triple-negative breast cancer (TNBC) is defined as breast cancer without detectable estrogen receptor (ER), progesterone receptor (PR), and human epidermal growth factor receptor 2 (HER2)/neu gene overexpression." (PMID 36178912, 2022). "Triple-negative breast cancer (TNBC) is immunohistochemically defined by the lack of expression of estrogen receptor (ER) and progesterone receptor (PR) and human epidermal growth factor receptor 2 (HER2)." (PMID 36188535, 2022). "Triple negative breast cancer (TNBC) is characterized by the lack of estrogen receptor, progesterone receptor, and HER2 and cannot be treated with the available hormone therapies and receptor targeted treatments." (PMID 35642054, 2022). "Triple-negative breast cancer (TNBC) is defined as the absence of estrogen receptor (ER) and progesterone receptor (PR) expression and human epidermal growth factor receptor (HER2) amplification." (PMID 35846145, 2022). "Triple negative breast cancer (TNBC) is defined by the absence of expression for oestrogen receptor (ER), progesterone receptor (PR) and human epidermal growth factor receptor-2 (HER2) which has limited targeted therapeutic options." (PMID 36405944, 2022). "Triple-negative breast cancer (TNBC), accounting for 10%–17% among all BCs, is a special subtype characterized by negative human epidermal growth factor receptor 2 (HER2), progesterone receptor (PR), and estrogen receptor (ER)." (PMID 35386285, 2022). "The estrogen receptor (ER), the progesterone receptor (PR) and the human epidermal growth factor 2 receptor (HER2) are absent in triple negative breast cancer (TNBC), making it one of the most aggressive types of breast cancer (HER2)." (PMID 35806035, 2022). "Triple-negative breast cancer (TNBC) is negative for estrogen receptor (ER), progesterone receptor (PR) and human epidermal growth factor receptor 2 (HER2), accounting for about 15%-20% of breast cancer." (PMID 35242718, 2022).
triple-negative breast carcinoma (continued). "Triple negative breast cancer (TNBC) accounts for 15-20% of breast cancer cases and is defined by the lack of estrogen receptor alpha (ERα) and progesterone receptor (PR) expression and the absence of Her2 overexpression/amplification." (PMID 35177654, 2022). "For the 15% triple-negative breast cancer (TNBC) patients whose tumor does not overexpress estrogen receptor, progesterone receptor, or HER2, they can only be treated with chemotherapy and surgery, have a worse prognosis, and are more likely to relapse." (PMID 35799609, 2022). "Triple-negative breast cancer (TNBC) is characterized by negative expression of estrogen (ER), progesterone receptor (PR), and human epidermal growth factor receptor 2 (HER2)." (PMID 36242046, 2022). "Triple-negative breast cancer (TNBC), characterized by the absence of estrogen receptor (ER), progesterone receptor (PR), and human epidermal growth factor receptor 2 (HER-2) expression, accounts for approximately 15% of all breast cancers." (PMID 35281097, 2022). "Triple-negative breast cancer (TNBC) represents the most aggressive subtype of breast cancer characterized by the absence of estrogen receptor (ER), progesterone receptor (PR) and human epidermal growth factor 2 (HER2)." (PMID 34991621, 2022). "Triple-negative breast cancer (TNBC) is generally defined by the lack of the expression of estrogen receptor (ER), progesterone receptor (PR), and HER2." (PMID 36042208, 2022). "Triple-negative breast cancer (TNBC) represents a special molecular subtype of breast cancer (BC) defined by the lack of three molecular biomarkers: estrogen receptor (ER), progesterone receptor (PR), and human epidermal growth factor receptor-2 (HER2)." (PMID 35214200, 2022). "Triple-negative breast cancer (TNBC) is classically defined by estrogen receptor (ER) and progesterone receptor (PR) immunohistochemistry expression <1% and absence of HER2 amplification/overexpression." (PMID 35817765, 2022). "Triple-negative breast cancer (TNBC) is characterized by the lack of expression of estrogen receptor (ER), progesterone receptor (PR), and human epidermal growth factor receptor 2 (HER2)." (PMID 35924147, 2022). "Triple negative breast cancer (TNBC) represents about 17% of all breast carcinomas and it is characterized by the absence of the estrogen receptor (ER), the progesterone receptor (PR) and human epidermal growth factor receptor 2 (HER2)." (PMID 35628518, 2022). "In breast cancer molecular subtypes, triple-negative breast cancer (TNBC) carrying the worst prognosis is defined by the lack of estrogen receptor (ER), progesterone receptor (PR), and human epidermal growth factor receptor 2 (HER2)." (PMID 33407498, 2021). "Triple-negative breast cancer (TNBC) is the most aggressive subtype of breast cancer, characterized by lack of estrogen receptor (ER), progesterone receptor (PR), or human epidermal growth receptor type 2 (HER2) expression." (PMID 34711841, 2021). "Triple-negative breast cancer (TNBC) is defined by the absence of estrogen receptor and progesterone receptor and human epidermal growth factor receptor 2 (HER2) overexpression." (PMID 34439290, 2021). "The triple-negative breast cancer (TNBC) subtype expresses none of the three receptors (ER and PgR absent, and HER2 negative, respectively) and is generally more aggressive and with a poorer prognosis than the other subtypes." (PMID 34944801, 2021). "Triple-negative breast cancer (TNBC) refers to breast cancers not expressing the oestrogen receptor (ER), the progesterone receptor (PR), or human epidermal growth factor receptor 2 (HER2)." (PMID 34134578, 2021). "Triple-negative breast cancer (TNBC), characterized by the absence of estrogen receptor (ER), progesterone receptor (PR), and human epidermal growth factor receptor 2 (HER-2), is a heterogenic and aggressive subtype of breast cancer." (PMID 34901016, 2021).
triple-negative breast carcinoma (continued). "Triple-negative breast cancer (TNBC), which is characterized by of the absence of expression of HER2, ER, and progesterone receptor (PR), is the most aggressive subtype and does not benefit from hormonal or targeted therapies." (PMID 33430896, 2021). "Triple-negative breast cancer (TNBC) is a heterogeneous group of tumors defined by the lack of expression of estrogen receptor (ER), progesterone receptor (PR), and Her2." (PMID 34253738, 2021). "One of the most aggressive subtypes is the basal-like, which belongs to the triple-negative breast cancer (TNBC) type, being negative for estrogen receptor (ER) (-), human epidermal growth factor receptor 2 (HER2) and progesterone receptor (PgR)." (PMID 33572458, 2021). "Only two women had triple negative breast cancer (ie were negative for HER2, estrogen receptor or progesterone receptor)." (PMID 33826649, 2021). "Triple-negative breast cancer (TNBC) is defined as a highly aggressive subtype of breast cancer, which lacks estrogen receptor (ER), progesterone receptor (PR) expression, and no amplification of human epidermal growth factor receptor 2 (HER2)." (PMID 34873403, 2021). "Triple negative breast cancer (TNBC) is an aggressive breast cancer subtype defined by lack of targetable estrogen receptor (ER), progesterone receptor (PR), and HER2." (PMID 34006255, 2021). "Triple-negative breast cancer (TNBC) is clinically defined as a breast cancer subtype that lacks expression of the estrogen receptor (ER) and progesterone receptor (PR) and has no amplification of HER2." (PMID 34207383, 2021). "Triple-negative breast cancer (TNBC) is diagnosed in cases where tumors are negative for ESR1, PGR, and HER2." (PMID 34408238, 2021). "This issue is augmented with triple-negative breast cancer (TNBC), which is characterized by the lack of expression of the estrogen receptor (ER) and progesterone receptor (PR), and lack of the overexpression of the epidermal growth factor receptor 2 (HER2)." (PMID 34298771, 2021). "Triple-negative breast cancer (TNBC) is an aggressive form of breast cancer (BC), defined by the lack of estrogen receptor (ER), progesterone receptor (PR), and human epidermal growth factor receptor 2 (HER2), which accounts for 15–20% of all BC cases." (PMID 34072442, 2021). "Triple-negative breast cancer (TNBC) is characterized by an absence of the estrogen receptor (ER), the progesterone receptor (PR), and HER-2 (human epidermal growth factor receptor 2)." (PMID 35008751, 2021). "Triple-negative breast cancer (TNBC), which was defined as no expression of estrogen receptor (ER), progesterone receptor (PR), and human epithelial growth factor receptor 2 (Her2) in breast tumor tissues, accounts for 10%–15% of breast tumor cases." (PMID 34686627, 2021). "Triple-negative breast cancer (TNBC) is a heterogeneous disease defined by the absence of estrogen receptor (ER) and progesterone receptor (PR) expression and human epithelial growth factor receptor 2 (HER2) amplification." (PMID 34725325, 2021). "Triple-negative breast cancer (TNBC) is a breast cancer subtype defined by the lack of expression for estrogen receptor (ER), progesterone receptor (PR), and human epidermal growth factor receptor 2 (HER2)." (PMID 34319041, 2021). "Triple-negative breast cancer (TNBC) is an aggressive subtype with the absence of estrogen receptor (ER), progesterone receptor (PR), and human epidermal growth factor receptor-2 (HER2)." (PMID 34631571, 2021). "The triple-negative breast cancer (TNBC) subtype, defined as negative for ER, PgR, and HER2, is biologically more aggressive and with a poorer prognosis than the other subtypes, in part due to the lack of suitable targeted therapies." (PMID 34944801, 2021).
triple-negative breast carcinoma (continued). "Triple-negative breast cancer (TNBC), characterized by the lack of estrogen receptor (ER), progesterone receptor (PR), and human epidermal growth factor receptor 2 (HER2/neu), is an aggressive subtype of breast cancer with limited treatment options." (PMID 34754037, 2021). "Triple negative breast cancer (TNBC) does not express human epidermal growth factor receptor 2 (HER2), estrogen receptor (ER) and progesterone receptor (PR)." (PMID 32856871, 2020). "Triple negative breast cancer (TNBC), a special clinical pathological subtype of breast cancer with negative expressions of estrogen receptor (ER), progesterone receptor (PR), and HER-2, accounts for about 10 to 20% of breast cancer." (PMID 32571245, 2020). "Triple negative breast cancer (TNBC) is clinically defined by the lack of the estrogen receptor (ER), progesterone receptor (PR), and human epidermal growth factor receptor 2 (HER2) expression." (PMID 32235297, 2020). "Triple negative breast cancer (TNBC) is defined as lacking expression of estrogen receptor (ER), progesterone receptor (PR) and epidermal growth factor receptor 2 (HER2)." (PMID 32355298, 2020). "The triple-negative breast cancer (TNBC) subtype is characterized as negative for the estrogen receptor 1 (ESR1), progesterone receptor (PGR), and human epidermal growth factor receptor type 2 (HER2)." (PMID 32806648, 2020). "The basal-like subtype is generally negative for estrogen receptor (ER), progesterone receptor (PR) and human epidermal growth factor receptor-2 (HER2), and therefore also called triple-negative breast cancer (TNBC)." (PMID 32652519, 2020). "Triple-negative breast cancer (TNBC) is a subgroup of breast cancer, which is defined as lack of estrogen receptor (ER), progesterone receptor (PR) and human epidermal growth factor receptor 2 (HER2)." (PMID 32264877, 2020). "Triple-negative breast cancer (TNBC) is defined as absence of estrogen receptor (ER), progesterone receptor (PR), and human epidermal growth factor receptor 2 (HER2) expression." (PMID 32637415, 2020). "Triple-negative breast cancer (TNBC) is characterized by the absence of estrogen receptor (ER), progesterone receptor (PR), and human epidermal growth factor receptor 2 (HER2)." (PMID 33204535, 2020). "Triple-negative breast cancer (TNBC) represents approximately 15–20% of all breast cancers that clinically are negative for the expression of estrogen receptor (ER), progesterone receptor (PR) and human epidermal growth factor receptor 2 (HER2) proteins." (PMID 32944002, 2020). "Triple-negative breast cancer (TNBC) is defined by the lack of the estrogen receptor (ER), progesterone receptor (PR), and human epidermal growth factor receptor 2 (HER2) expression." (PMID 33213491, 2020). "Our previous studies demonstrated that SBC in TA2 mice belongs to triple-negative breast cancer (TNBC), which is negative for estrogen receptor (ER), progesterone receptor (PR), and human epidermal growth factor receptor 2 (HER-2) expression." (PMID 32432040, 2020). "Triple-negative breast cancer (TNBC) refers to a subgroup of breast cancer (BC) defined by the lack of estrogen receptor (ER), progesterone receptor (PR), and human epidermal growth factor receptor 2 (HER2)." (PMID 33088912, 2020). "Triple-negative breast cancer (TNBC) is a subtype of BC in which the estrogen receptor (ER) and progesterone receptor (PR) are not expressed, and the human epidermal growth factor receptor 2 (HER2) is not amplified or overexpressed either." (PMID 34138297, 2020). "Triple-negative breast cancer (TNBC) is defined by a lack of estrogen receptor (ER), progesterone receptor (PR), and human epidermal growth factors receptor 2 (HER2)." (PMID 32770025, 2020). "Triple-negative breast cancer (TNBC) is a type of breast malignancy that is negative for the expression of estrogen receptor (ER), progesterone receptor (PR), and human epidermal growth factor 2 (HER2)." (PMID 32928141, 2020).